RHNO1 (RAD9-HUS1-RAD1 interacting nuclear orphan 1)
Description:
Involved in microhomology-mediated end-joining (MMEJ) DNA repair by promoting recruitment of polymerase theta (POLQ) to DNA damage sites during mitosis. MMEJ is an alternative non-homologous end-joining (NHEJ) machinery that takes place during mitosis to repair double-strand breaks in DNA that originate in S-phase. Accumulates in M-phase; following phosphorylation by PLK1, interacts with POLQ, enabling its recruitment to double-strand breaks for subsequent repair. Also involved in the DNA damage response (DDR) signaling in response to genotoxic stresses such as ionizing radiation (IR) during the S phase. Recruited to sites of DNA damage through interaction with the 9-1-1 cell-cycle checkpoint response complex and TOPBP1 in a ATR-dependent manner. Required for the progression of the G1 to S phase transition. Plays a role in the stimulation of CHEK1 phosphorylation.
Synonyms: C12orf32; RHINO; HKMT1188; MGC13204
Tractability: PROTAC: UniProt records ubiquitination sites on it.
Gene: Protein-coding gene on chromosome 12 (2,876,258 to 2,889,524, forward strand). Ensembl gene ENSG00000171792.
Subcellular location: Nucleus; Chromosome
Pathways (Reactome):
DNA Repair: HDR through Single Strand Annealing (SSA); Presynaptic phase of homologous DNA pairing and strand exchange; Processing of DNA double-strand break ends
Cell Cycle: G2/M DNA damage checkpoint
Disease: Impaired BRCA2 binding to RAD51
Gene Ontology:
Molecular function: chromatin-protein adaptor activity; protein binding
Biological process: cellular response to ionizing radiation; cellular response to UV; DNA damage checkpoint signaling; double-strand break repair via alternative nonhomologous end joining; positive regulation of G0 to G1 transition; protein localization to site of double-strand break; recombinational repair; chromatin organization
Cellular component: chromatin; chromosome; nucleus; site of double-strand break; nucleoplasm
Genetic constraint (gnomAD): Loss-of-function variants: 10 observed, 9.7 expected, observed/expected ratio (o/e) 1.03, 90% interval 0.63 to 1.69. That is too few expected variants to judge how well the gene tolerates losing a copy. Missense variants: 292 observed, 295.23 expected, observed/expected ratio (o/e) 0.99, 90% interval 0.9 to 1.09. Synonymous variants: 95 observed, 111.96 expected, observed/expected ratio (o/e) 0.85, 90% interval 0.72 to 1.01.
Homologues: Orthologues: chimpanzee RHNO1 (99% identical), macaque RHNO1 (95% identical), rabbit RHNO1 (76% identical), pig RHNO1 (73% identical), dog RHNO1 (70% identical), mouse Rhno1 (68% identical), guinea pig RHNO1 (63% identical), rat Rhno1-ps2 (62% identical), rat Rhno1 (55% identical), tropical clawed frog rhno1 (31% identical).
Diseases named in the same sentence as RHNO1 in open-access papers:
RHNO1 is named in the same sentence as 11 diseases in open-access papers, as found by Europe PMC text mining. Sharing a sentence is not in itself a finding about the gene and the disease. The quoted sentences say what the papers report.
breast carcinoma (3 papers, 2014 to 2021). "The initial report of RHNO1 (first called C12orf32) showed that it was overexpressed in a breast cancer cell line, localized to the nucleus, and promoted cell survival." (PMID 33890574, 2021).
ovarian carcinoma (3 papers, 2020 to 2025). A malignant neoplasm originating from the surface ovarian epithelium. "In another study, co-regulation and functional co-operativity of a H2H pair, FOXM1 and RHNO1, was also proved in ovarian cancer." (PMID 33488665, 2020). "To address whether FOXM1 and RHNO1 expression correlates in biological contexts unrelated to ovarian cancer or its progenitor cells, we analyzed in silico gene expression data sets, including normal and cancer tissues and cells, and mouse and human data." (PMID 33890574, 2021). "Finally, regarding the timing of these events in ovarian cancer, it is known that FOXM1 is expressed in HGSC precursor lesions in the FTE, which may, along with other proteins such as cyclin E1, increase RS, thus providing a selective advantage for RHNO1 co-expression." (PMID 33890574, 2021).
colorectal cancer (2 papers, 2021 to 2024). A primary or metastatic malignant neoplasm that affects the colon or rectum. "The expression, regulation, and function of RHNO1 in normal tissues and cancer are largely unknown, but RHNO1 was recently identified as a hub gene associated with poor prognosis in colorectal cancer." (PMID 33890574, 2021). "RHNO1 has been recently reported as a prognostic marker in colorectal cancer, renal, and liver cancer, where the high expression is associated with a poor prognosis." (PMID 38604503, 2024).
pancreatic cancer (2 papers, 2018 to 2025). "Interestingly, truncation mutations of RHNO1 that eliminate the region of the protein in which this putative phosphorylation site occurs, and which are therefore unlikely to be unable to bind TOPBP1, have been identified in a number of families with hereditary pancreatic cancer." (PMID 30295604, 2018).
metastatic tumors (1 paper, 2021). "Both FOXM1 and RHNO1 were overexpressed in each category of cancer samples (primary tumors, metastatic tumors, and recurrent tumors) as compared to normal tissues." (PMID 33890574, 2021).
serous carcinoma (1 paper, 2021). "FOXM1 and RHNO1 each promote high-grade serous carcinoma cell clonogenic growth." (PMID 33890574, 2021). "(B) Correlation of FOXM1 and RHNO1 promoter activity in Fallopian tube epithelium (FTE) (FT282) and high-grade serous carcinoma (HGSC) cell lines (OVCAR5, COV318, OVCAR4, Kuramochi, SNU119)." (PMID 33890574, 2021). "OVCAR8 high-grade serous carcinoma cells were engineered for doxycycline (dox)-inducible FOXM1 and/or RHNO1 shRNA knockdown." (PMID 33890574, 2021).
tumor (5 papers, 2016 to 2026). "This work identifies RHNO1 as a key component in the cellular replication stress response and highlights its potential as a therapeutic target for tumor cells reliant on ATR/Chk1 signaling." (PMID 42239230, 2026). "Moreover, FOXM1 showed greater overexpression in tumor tissues compared to RHNO1, and, consistently, the FOXM1/RHNO1 expression ratio was elevated in cancer." (PMID 33890574, 2021). "Moreover, the ubiquity of elevated RS in HGSC makes this tumor type particularly relevant for RHNO1 investigation." (PMID 33890574, 2021). "Although PGM2 and RHNO1 have not been reported in CRC, they are involved in other tumor developments." (PMID 33537062, 2020).
cancer (4 papers, 2018 to 2026). A tumor composed of atypical neoplastic, often pleomorphic cells that invade other tissues. "Here, we investigated the roles of RAD9-HUS1-RAD1 interacting nuclear orphan 1 (RHNO1) in cancer progression and its involvement in maintaining ATR/Chk1 signaling during the DNA replication stress response." (PMID 42239230, 2026). "We show that FOXM1 and RHNO1 are tightly co-expressed in both normal and cancer cells and tissues, including individual cells, and that their co-expression is controlled by a bidirectional promoter (F/R-BDP)." (PMID 33890574, 2021). "Together, these data, along with the large elevation of RHNO1 expression seen in cancer vs. normal, suggest that cancer cells have a greater dependency on RHNO1 than do normal cells." (PMID 33890574, 2021). "FOXM1 and RHNO1 mRNA expression correlate in both normal tissues and cancer, including HGSC, and is one of the most highly correlated BDG pairs genome-wide in FTE and HGSC cell models." (PMID 33890574, 2021). "In agreement, after normalization to the canonical cell proliferation marker MKI67, the FOXM1/RHNO1 expression ratio was similar in normal and cancer tissues." (PMID 33890574, 2021). "The prominence of the RS response in cancer cell survival and its recent emergence as a therapeutic target make investigation of the function of RHNO1 in cancer an important area of study." (PMID 33890574, 2021). "This, along with conservation of the F/R-BDP in vertebrates, suggests that FOXM1 and RHNO1 function cooperatively in normal physiology and cancer." (PMID 33890574, 2021). "To address this question, we compared FOXM1 and RHNO1 expression in Genotype-Tissue Expression (GTEx) normal tissues vs. TCGA pan-cancer tissues using the Toil method." (PMID 33890574, 2021). "Additionally, our data showing frequent genomic amplification of RHNO1 in HGSC is consistent with recent observations that DDR genes are frequently amplified in human cancer." (PMID 33890574, 2021). "We postulate that cancer cells have a selective advantage for FOXM1 and RHNO1 co-expression since FOXM1 drives RS and downstream oncogenic phenotypes such as genomic instability, while RHNO1 helps mitigate FOXM1-induced RS to a level more favorable to cancer cell survival." (PMID 34205406, 2021). "While FOXM1 is overexpressed in HGSC and pan-cancer, RHNO1 expression in normal tissues vs. cancer is unknown." (PMID 33890574, 2021). "Whether specific transcription factors symmetrically or asymmetrically regulate F/R-BDP activity is a key question as the FOXM1/RHNO1 expression ratio increased in cancer vs. normal." (PMID 33890574, 2021). "Overall, this conceptual framework may prove useful to guide future studies of FOXM1 and RHNO1 and their interplay in normal physiology and cancer." (PMID 33890574, 2021). "To determine whether copy number status associates not only with FOXM1 but also RHNO1 expression in HGSC, we analyzed TCGA and Cancer Cell Line Encyclopedia (CCLE) data." (PMID 33890574, 2021). "FOXM1 and RHNO1 are one of the first examples of oncogenic BDG, and therapeutic targeting of FOXM1/RHNO1 BDG is a potential therapeutic approach for ovarian and other cancers." (PMID 33890574, 2021). "However, the present study demonstrates that individual targeting of either FOXM1 or RHNO1, using shRNA or CRISPR-Cas9, significantly reduces HGSC cell clonogenic growth, suggesting that each protein contributes to cancer phenotypes." (PMID 33890574, 2021). "Based on these data, we hypothesize that the FOXM1/RHNO1 BDG pair promotes HGSC and other cancers, and is a potential target for cancer therapeutic intervention." (PMID 33890574, 2021).
RHNO1 also shares sentences with these, for which no sentence is quoted: COVID-19 (1 paper); liver cancer (1); serous ovarian cancer (1).